TSLP (thymic stromal lymphopoietin)
Diseases named in the same sentence as TSLP in open-access papers (continued):
Sharing a sentence is not in itself a finding about the gene and the disease.
allergic disease (continued). "Most reports involve TSLP in B cell homeostasis and/or B cell development, together with its implication in the development of allergic diseases." (PMID 20174635, 2010). "Moreover, TSLP is considered as a key factor contributing to the onset and aggravation of allergic diseases." (PMID 41576104, 2026). "Indeed, during allergy and anti-helminth immunity, epithelial cells of damaged barriers release alarmins including IL-25, IL-33, and thymic stromal lymphopoietin (TSLP), but also chemokines such as CXCL1 and CCL11, to promote cell recruitment and inflammation." (PMID 40943268, 2025). "TSLP is a cytokine involved in the context of inflammation and allergy." (PMID 40475767, 2025). "Though CAPN14 likely contributes to the tissue specificity of EoE, the EoE risk genes TSLP, EMSY, LRRC32, and CLEC16A are hypothesized to have roles in numerous allergic diseases." (PMID 40470207, 2025). "Elevated TSLP levels, consistent with prior research, highlight its function in allergic diseases." (PMID 39860604, 2025). "In addition to allergy, TSLP is found to be abundant in autoimmune diseases such as psoriasis and rheumatoid arthritis." (PMID 38512921, 2024). "TSLP is a relevant player in EoE and other type 2 inflammatory and allergic diseases." (PMID 38256003, 2024). "TSLP is a cytokine that plays a pivotal role in the initiation and maintenance of immune responses, particularly within the context of skin inflammation and allergic reactions." (PMID 39717176, 2024). "Thus, the blockade of TSLP represents an attractive therapeutic strategy for allergic diseases and cancer." (PMID 38566968, 2024). "These are common in other allergic diseases, and usually involve changes in the abundance or composition of the esophageal microbiome in adaptive responses, with epithelial cells releasing alarmins such as IL-25, IL-33, and thymic stromal lymphopoietin (TSLP)." (PMID 38256003, 2024). "Although TSLP inhibitors are currently more used in the treatment of allergic diseases, the role of TSLP as a pro-inflammatory mediator in RA has been discovered, and it is also involved in the autoimmune response of some diseases, so the role of TSLP on AIDs would gradually be revealed." (PMID 37859999, 2023). "Several studies reported a rise in TSLP in allergic diseases." (PMID 36724763, 2023). "In our previous study, we focused on thymic stromal lymphopoietin (TSLP), a key cytokine that initiates and promotes the development of Th2 immune responses and that has been implicated in the progression of various allergic diseases." (PMID 37935734, 2023). "With the rapid development of immunology, molecular biology, and biotechnology, many new biological drugs have been designed for the treatment of allergic diseases, including anti-immunoglobulin E (IgE), anti-interleukin (IL)-5, and anti-thymic stromal lymphopoietin (TSLP)/IL-4, to control symptoms." (PMID 36964157, 2023). "Subsequently, TSLP-activated DCs also stimulate naive CD4+ T cells to differentiate into T follicular helper cells (defined by expression of IL-21, CXCR5, CXCL13 and BCL6), which can induce IgG and IgE secretion by memory B cells, linking TSLP to IgE production in allergy." (PMID 37628907, 2023). "The discovery that SH-340 can effectively inhibit TSLP opens up new avenues for designing innovative treatments that could attenuate allergic reactions." (PMID 37630370, 2023). "Suppression of the TSLP signaling and lack of basophil-derived IL-4 synthesis was found to inhibit food-induced allergic reaction in the intestine confirming the crucial role of TSLP-basophil-IL-4 axis in epicutaneous sensitization and associated pathogenesis of IgE-mediated food allergy." (PMID 36904070, 2023). "Clinically, SH-340′s ability to suppress TSLP suggests a potential breakthrough in treating a range of allergic diseases, offering a novel therapeutic angle that could complement or even surpass existing approaches." (PMID 37630370, 2023).
allergic disease (continued). "TSLP, an IL-7-like cytokine, is a characteristic role of allergic diseases." (PMID 36724763, 2023). "TSLP, also known as an epithelium-derived proinflammatory cytokine, was demonstrated to be a master regulator of allergic airway inflammation and acted a pivotal role in the pathogenesis of allergic diseases, including AR." (PMID 37207043, 2023). "The possible mechanism may be that the epigenetic imbalance of thymic stromal lymphopoietin is involved in the programming of vitamin D-related allergic diseases." (PMID 35432712, 2022). "TSLP stimulated-DC could specifically induce Th2 induction, which has been widely described in allergic diseases." (PMID 36076269, 2022). "Moreover, analysis conducted using genetically modified mice has revealed that TSLP is a master switch for the development of allergic diseases." (PMID 35159975, 2022). "As a result of emerging evidence, IL-25, IL-33, and TSLP are important mediators of inflammation during allergic disease and may prove to be key targets for therapeutic intervention." (PMID 35406669, 2022). "TSLP can be produced by epithelial cells, smooth muscle cells and mast cells in allergic diseases." (PMID 35292112, 2022). "Therefore, inhibition of the TSLP signaling pathway has the potential to exert significant clinical effects on allergic diseases." (PMID 36355519, 2022). "Notably, a mix of anti-IL-33, anti-TSLP and anti-IL-25 prevented egg allergy induction and suppressed ongoing disease." (PMID 36660742, 2022). "Therefore, TSLP is considered a therapeutic target for the treatment of allergic diseases, including AD." (PMID 35563251, 2022). "In addition to priming inflammatory Th2 response, TSLP-mDCs also play an important role in maintaining and further polarizing Th2 memory cells in allergic disease via an OX40L-dependent manner." (PMID 34305908, 2021). "This study also found a positive correlation between TSLP methylation and MEP in urine, which was inconsistent with our assumptions that phthalate exposure may result in the hypomethylation of TSLP and thereby induces allergic diseases." (PMID 33836808, 2021). "To date, although it has been recognized that high TSLP expression is one of the important cytokines to initiate skewed Th2 responses and plays a critical role in the pathogenesis of allergic diseases 26, how the TSLP expression is sustained at high levels in epithelial cells remains elusive." (PMID 34131408, 2021). "The role of IL-25, IL-33 and TSLP in various allergic diseases has been studied for several years." (PMID 34301307, 2021). "Recognizing the significant effect of TSLP, IL-25 and IL-33 on the pathogenesis and development of allergic diseases and the effect of elevated concentrations of these alarmins on the number of allergen components to which the patient was sensitized was analyzed in the ImmunoCap ISAC test." (PMID 34301307, 2021). "However, as our best knowledge, this is the first study to indicate the underlying mechanism between phthalate exposure and childhood allergy in term of DNA methylation of TSLP gene, which plays an important role in the mechanism of allergic disease." (PMID 33836808, 2021). "Thus, TSLP is essential in inducing the differentiation of naïve T cells into TH2 cells in the pathogenesis of allergic diseases." (PMID 33836808, 2021). "TSLP is expressed by keratinocytes in response to certain microbial products, trauma, or inflammatory cytokines, and keratinocyte-derived TSLP helps promote Th2 cell differentiation and inflammation in allergic diseases." (PMID 33055429, 2020). "In addition, in the asthmatic allergy model, it was shown that TSLP directly and selectively impairs IL-10 production of Treg and inhibits their suppressive activity." (PMID 32435245, 2020). "Additionally, both OX‐40L and CCL17 in DCs can trigger Th2 polarization, which induces a low inflammatory response and plays a protective role in allergy under the effect of thymic stromal lymphopoietin." (PMID 32406154, 2020).
allergic disease (continued). "Increased levels of TSLP protein are found in skin lesions of patients with atopic dermatitis and aberrant expression of TSLP has been observed in allergic diseases of the gastrointestinal tract, including Crohn’s disease, eosinophilic oesophagitis and ulcerative colitis, and in cancer." (PMID 33050934, 2020). "Thus, the regulation of TSLP in keratinocytes is thought to be important to prevent the development of severe allergic reactions." (PMID 31817146, 2019). "We have previously reported the restoration of the epithelial barrier function by inhibiting the expression of key promoters of allergy (thymic stromal lymphopoietin [TSLP] and interleukin 33 [IL-33]), which contribute to the Th2 immune response observed in early AD9." (PMID 31767859, 2019). "TSLP supports the production of IL-5 and IL-13 by lung ILC2s, which contributes to eosinophilia and elevated mucus production in papain and chitin models of allergy induction." (PMID 31921158, 2019). "Thus, it is important to keep hypoxia in epithelial tissues to avoid the onset and exacerbation of allergy via downregulating TSLP and enhancing filaggrin expressions." (PMID 31682627, 2019). "Because LA possesses a wide range of pharmacological properties, being antispasmodic, anti-inflammatory, and anti-hyperpigmentation, we hypothesized that LA could inhibit TSLP, which is an important factor in allergic diseases." (PMID 30011850, 2018). "TSLP, secreted by the bronchial epithelial cells, is the main switch of allergic disease." (PMID 29250125, 2017). "TSLP is increasingly gaining a central role in the pathophysiology of allergic diseases." (PMID 28368013, 2017). "We tested whether YQPC could prevent the occurrence of an allergy by suppressing the expression of TSLP upstream of the TSLP-DC-TH2 axis." (PMID 29250125, 2017). "By looking at the intersection of allergic disease associated SNPs and Barrier-deficient peaks in our ESS model, we markedly reduced the number of regions which could contribute to regulation of TSLP after barrier injury." (PMID 28953906, 2017). "We envisage that the structural and mechanistic framework and the molecular tools presented here will facilitate targeted interrogation of TSLP signalling in vitro and in animal models, and will guide therapeutic approaches that manipulate human TSLP-mediated signalling to treat allergic diseases." (PMID 28368013, 2017). "Moreover, DCs activated by TSLP enhance allergy-promoting Th2 memory cells by increasing the number of their receptors for IL-25." (PMID 27069818, 2016). "Although TSLP, IL-25, and IL-33 have all been shown the contribute to the induction of Th2 responses, there seems to be a division of labour where each of the mediators can have a more prominent role depending on the allergy model under investigation." (PMID 27050744, 2016). "We hypothesized that AS-IV could regulate the key pro-allergic cytokines IL-33 and TSLP derived from ECs and as a consequence, inhibits the occurrence and development of allergic diseases." (PMID 27917896, 2016). "Also, TSLP has been found to modulate allergy through antigen exposure on the skin and subsequent allergic reactions similar to our model." (PMID 26793299, 2015). "TSLP may therefore play a central role not only in the development of AD, but also in the development of other allergic diseases." (PMID 25866638, 2015). "Immunoglobulin E, thymic stromal lymphopoietin (TSLP), and interleukin-33 (IL-33) may be implicated in the etiology of childhood allergy and are detectable at birth." (PMID 26084354, 2015). "TSLP has also been recently recognized for its role in childhood allergy." (PMID 26084354, 2015). "It was presumed that the key mechanism involved in the reduction of allergy recurrence by YPFS might be related to regulation of TSLP derived from ECs." (PMID 25198676, 2014).
allergic disease (continued). "TSLP derived from ECs is a key allergic inflammation master switch, suggesting that it is the most important target interfering with the initial phase of allergic diseases." (PMID 25198676, 2014). "IL-33, IL-25 and thymic stromal lymphopoietin (TSLP) are thought to share several roles in immune responses, such as induction of Th2 cytokines by Th2 cells, suggesting that these cytokines contribute to the development of allergic diseases." (PMID 24205109, 2013). "The inhibitory effects of XQLT on NGF, p75NTR and TSLP may be associated with the TLR4 pathway, thus providing pharmacological targets for investigations into how XQLT affects the early phase of allergic reactions." (PMID 24223644, 2013). "In conclusion, XQLT may regulate NGF, p75NTR and TSLP via the TLR4 pathway in the early phase of an allergic reaction." (PMID 24223644, 2013). "It is difficult to predict the role of TSLP activation of eosinophils in allergic diseases, when so many other factors are present that could similarly promote eosinophil degranulation and activation." (PMID 22838633, 2012). "Overall, these findings suggest that although the TSLP gene presents itself as a good candidate involved in the development of allergy, this gene is unlikely to be associated with increased susceptibility to AR in Han Chinese subjects." (PMID 22973903, 2012). "In addition, our results also found an association between serum TSLP levels and clinical remission independent of confounding factors such as lung function measurements or allergy sensitization." (PMID 40503233, 2025). "Concomitantly, the level of TSLP in the blood may also increase due to an allergic reaction." (PMID 37175425, 2023). "Given the evidence for multiple functions of TSLP in diseases beyond allergy, it is possible that tezepelumab may have beneficial impact on some of these diseases as well, and further study is warranted regarding targeting TSLP in a broader range of conditions." (PMID 37165746, 2023). "This could be explained by the fact that Zymozan-, PAM3-, LPS-, HKSA- and Curdlan-cDC2 contexts are mimicking an external pathogen, of fungal or bacterial origin, while TSLP is acting as an inflammatory cytokine produced by epithelial cells or stromal cells, in the context of allergy." (PMID 34983927, 2022). "Hence, TSLP signaling inhibitors can be used as materials for the development of allergy drugs." (PMID 34443392, 2021). "The unique inflammatory Th2-polarizing property of surface OX40L expressed by TSLP-mDCs not only exemplifies the functional plasticity of DCs in inducing distinct T helper cell responses, but also underscores the critical role of DCs in the pathogenesis of allergic diseases." (PMID 34305908, 2021). "Therefore, we suppose that IL-35 may be involved in allergic diseases by regulating the expression of TSLP, IL-33, and IL-25 from HNECs." (PMID 34899052, 2021). "Interestingly, since TSLP induction occurs through epithelial Toll-like receptors, TSLP-mediated allergic manifestations represent an important link between innate immunity and allergic disease." (PMID 30631320, 2018). "On one hand, TSLP plays a critical role in maintaining the intestinal immune homeostasis by shaping the anti-inflammatory features of dendritic cells and Treg; on the other, strong evidence suggested that its over-expression is instrumental for the development of allergic reactions." (PMID 29896198, 2018). "Thus, the TSLP genetic variants may result in a decrease in the expression and activity of the TSLP protein that gives a protective effect for the development of AD and allergy." (PMID 30304837, 2018). "Indeed, the idea that skin epithelium can trigger the onset of allergic diseases is supported by the findings that thymic stromal lymphopoietin (TSLP) can endow dendritic cells (DCs) with the ability to create a type 2-permissive microenvironment and drive a T-cell-mediated allergic immune response." (PMID 27853507, 2016).
allergic disease (continued). "We hypothesized that AS-IV exerts its anti-allergy effects by regulating the production of key pro-allergic cytokines based on the fact that interleukin (IL)-33 and thymic stromal lymphopoietin (TSLP) levels increase significantly in the initial stage of the sensitization phase." (PMID 27917896, 2016). "Thus, TSLP has been clearly demonstrated as a key factor for the development of allergic disease." (PMID 23437132, 2013). "Furthermore, two important Th2 innate cells, activated eosinophils and basophils, secrete bioactive IL-25, which could up-regulate TSLP, indicating cross-talk between immune cells and structural cells related to allergic disease." (PMID 23437132, 2013). "TSLP can stimulate the activation of primary human CD1c+ dendritic cells with the increased secretion of CCL17, a chemokine which is involved in many allergy and inflammation reactions." (PMID 39726595, 2024). "Thymic stromal lymphopoietin (TSLP), a type I cytokine in the IL-2 family, is recognized as a key contributor to the pathogenesis of various allergic diseases." (PMID 39456451, 2024). "Cytokines including thymic stromal lymphopoietin (TSLP), serotonin (5-HT), IL-33, and endothelin (ET-1) also mediate this allergic reaction." (PMID 33708782, 2021). "Thymic stromal lymphopoietin (TSLP) is expressed primarily by epithelial cells, and induces inflammation at the time of tolerance failure in allergic disease." (PMID 32211586, 2020). "Thymic stromal lymphopoietin (TSLP) plays an important role in the differentiation and proliferation of Th2 cells, resulting in eosinophilic inflammation and numerous allergic diseases." (PMID 31217492, 2019). "Airway epithelial cell-derived thymic stromal lymphopoietin (TSLP) and IL-33 can enhance lung-resident group 2 innate lymphoid cells (ILC2s), and they play an important role in the development of allergic diseases." (PMID 28819104, 2017). "Thymic stromal lymphopoietin (TSLP) produced by epithelial cells acts on dendritic cells (DCs) to drive differentiation of TH2‐cells, and is therefore important in allergic disease pathogenesis." (PMID 26573878, 2016). "The roles of TSLP and IL33 in allergy were evaluated in TSLP receptor (TSLPR)- and IL33 receptor-deficient (T1/ST2) mice, respectively; TSLPR- and T1/ST2-knockout mice showed strong Th1 responses with high levels of IL2 and IFN-γ and impaired the Th2 response." (PMID 27826297, 2016). "Increased ratio of proinflammatory cytokines (IL-17, TSLP, and IL-6) versus regulatory cytokines (IL-10 and TGF-β) in severe allergic diseases would activate further the balance shift and form a positive feedback loop in chronic inflammation." (PMID 23283296, 2008). "Another study links the release of the EETs to the thymic stromal lymphopoietin (TSLP), a cytokine that is expressed in the epithelial cells of the intestine, airways, and skin, and is upregulated in bronchial asthma, dermatitis, and allergy." (PMID 40264103, 2025). "TSLP-stimulated DCs also orchestrate the homeostatic expansion of allergen-specific Th2 memory cells as well as prompt the Th2 phenotype polarization via interaction with OX40L, thus contributing to the maintenance of chronic allergy-related inflammation." (PMID 37096155, 2023). "Although TSLP was produced in both allergy-negative and -positive patients, TSLP, TSLPR and TNF-α were all produced at significantly higher quantities in the mucosal epithelium samples of the former." (PMID 35159975, 2022). "In an ovalbumin-induced food allergy model, TSLP-induced food allergy was dependent on the presence of IL-33, but IL-33 driven allergy was independent of TSLP." (PMID 36660742, 2022). "Release of TSLP, IL-33, IL-25 and GM-CSF is obviously not restricted to allergy; however, these cytokines mostly contribute to type 2 immune response through specific activation of dendritic cells." (PMID 34084159, 2021).